DELEC1 (deleted in esophageal cancer 1)
Description:
Candidate tumor suppressor.
Synonyms: CTS9; DEC1
Gene: Long non-coding RNA gene on chromosome 9 (114,850,968 to 115,402,644, forward strand). Ensembl gene ENSG00000173077.
Diseases named in the same sentence as DELEC1 in open-access papers:
DELEC1 is named in the same sentence as 5 diseases in open-access papers, as found by Europe PMC text mining. Sharing a sentence is not in itself a finding about the gene and the disease. The quoted sentences say what the papers report.
depression (1 paper, 2024). "Additional studies are required to better understand the sex-specific functions of DELEC1 and ZBTB20 in depression and addiction." (PMID 39766481, 2024).
substance abuse (1 paper, 2024). The use of a drug for a reason other than which it was intended or in a manner or in quantities other than directed. "While the role of DELEC1 in circadian rhythms or substance abuse remains uncertain, it may contribute to tumor suppression and has been implicated in female depression in a recent study." (PMID 39766481, 2024).
tumor (3 papers, 2023 to 2025). "For instance, GACAT3, generally associated with elevated expression in breast cancer tissues, was hypermethylated despite its usual upregulation in malignancies, whereas DELEC1, a known tumor suppressor, exhibited hypermethylation correlating with reduced gene activity." (PMID 40566344, 2025). "LncRNAs such as GACAT3, DELEC1, CASC2, and LCIIAR exhibited altered methylation status under PFOS exposure, suggesting potential disruption of tumor-suppressive functions or promotion of malignant phenotypes." (PMID 40566344, 2025). "DEC1 (deleted in esophageal cancer 1, DELEC1), a lncRNA gene, is a candidate tumor suppressor, which means that it may regulate the cell cycle and other fundamental cellular processes." (PMID 36970523, 2023).
cancer (1 paper, 2021). A tumor composed of atypical neoplastic, often pleomorphic cells that invade other tissues. "In the context of cancer, TGF‐β induces BHLHE40, which encodes deleted in esophageal cancer 1 (DEC1) to promote survival of mammary carcinoma cells." (PMID 33342034, 2021).
DELEC1 also shares sentences with these, for which no sentence is quoted: esophageal cancer (3 papers).